VHL (von Hippel-Lindau tumor suppressor)
Description:
Involved in the ubiquitination and subsequent proteasomal degradation via the von Hippel-Lindau ubiquitination complex. Seems to act as a target recruitment subunit in the E3 ubiquitin ligase complex and recruits hydroxylated hypoxia-inducible factor (HIF) under normoxic conditions. Involved in transcriptional repression through interaction with HIF1A, HIF1AN and histone deacetylases. Ubiquitinates, in an oxygen-responsive manner, ADRB2. Acts as a negative regulator of mTORC1 by promoting ubiquitination and degradation of RPTOR.
Synonyms: VHL1; HRCA1; RCA1; pVHL
Tractability: Small molecule: a structure with a bound ligand is known; a high-quality ligand is known. Antibody: UniProt places it where antibodies can reach, with high confidence; its Gene Ontology location is reachable by antibodies, with medium confidence. PROTAC: it is named in the literature on targeted protein degradation; ubiquitination databases record sites on it; its protein half-life has been measured; a small molecule that binds it is known.
Chemical probes: CM11 (high quality), VH298 (high quality)
Safety:
Unwanted effects reported when the protein is acted on. In parentheses: how it was acted on, where the effect was seen, and who reports it.
Liver Cancer (activation; source: AOP-Wiki)
Gene: Protein-coding gene on chromosome 3 (10,141,778 to 10,153,676, forward strand). Ensembl gene ENSG00000134086.
Subcellular location: Cytoplasm (Isoform 1); Cell membrane; Endoplasmic reticulum; Nucleus; Cytoplasm (Isoform 3)
Subcellular location (Human Protein Atlas): Nucleoplasm; Cytosol; Microtubules; Primary cilium; Primary cilium tip
Pathways (Reactome):
Disease: Replication of the SARS-CoV-1 genome; Replication of the SARS-CoV-2 genome
Metabolism of proteins: Neddylation; SUMOylation of ubiquitinylation proteins
Cellular responses to stimuli: Oxygen-dependent proline hydroxylation of Hypoxia-inducible Factor Alpha
Immune System: Antigen processing: Ubiquitination & Proteasome degradation
Signal Transduction: RHOBTB3 ATPase cycle
Gene Ontology:
Molecular function: DNA-binding transcription factor binding; enzyme binding; molecular adaptor activity; protein binding; protein serine/threonine kinase binding; transcription corepressor activity; transcription elongation factor activity; ubiquitin-like ligase-substrate adaptor activity; ubiquitin-protein transferase activity
Biological process: amyloid fibril formation; negative regulation of autophagy; negative regulation of cell population proliferation; negative regulation of gene expression; negative regulation of receptor signaling pathway via JAK-STAT; negative regulation of signal transduction; negative regulation of TORC1 signaling; negative regulation of transcription by RNA polymerase II; negative regulation of transcription elongation by RNA polymerase II; positive regulation of DNA-templated transcription; proteasome-mediated ubiquitin-dependent protein catabolic process; protein ubiquitination; regulation of cellular response to hypoxia; regulation of DNA-templated transcription; regulation of gene expression; cell morphogenesis; cellular response to hypoxia; negative regulation of apoptotic process; positive regulation of cell differentiation; protein stabilization; proteolysis
Cellular component: Cul2-RING ubiquitin ligase complex; cytoplasm; cytosol; endoplasmic reticulum; nucleoplasm; nucleus; plasma membrane; mitochondrion
Genetic constraint (gnomAD): Loss-of-function variants: 13 observed, 20.95 expected, observed/expected ratio (o/e) 0.62, 90% interval 0.4 to 0.99. The synonymous counts are far from expectation, so gnomAD's model fits this gene poorly and the ratio says little. Missense variants: 328 observed, 276.24 expected, observed/expected ratio (o/e) 1.19, 90% interval 1.08 to 1.3. Synonymous variants: 167 observed, 125.13 expected, observed/expected ratio (o/e) 1.33, 90% interval 1.18 to 1.52.
Gene-disease validity (ClinGen):
ClinGen rates the evidence that VHL causes each of these diseases.
von Hippel-Lindau disease (autosomal dominant): Definitive. An autosomal dominant disorder caused by pathogenic variants in the VHL gene, leading to an increased risk of various benign and malignant tumors, including hemangioblastomas, retinal hemangiomas, endolymphatic sac tumors, renal cell carcinoma, and pheochromocytomas.
Cancer hallmarks: angiogenesis (suppresses); change of cellular energetics (promotes); suppression of growth (promotes); escaping programmed cell death (suppresses); invasion and metastasis (suppresses)
Homologues: Orthologues: chimpanzee VHL (100% identical), macaque VHL (96% identical), rat Vhl (74% identical), guinea pig VHL (73% identical), mouse Vhl (71% identical), rabbit VHL (70% identical), tropical clawed frog vhl (46% identical), zebrafish vhl (38% identical), Drosophila melanogaster Vhl (17% identical). Paralogues in human: VHLL (42% identical).
Diseases named in the same sentence as VHL in open-access papers:
VHL is named in the same sentence as 347 diseases in open-access papers, as found by Europe PMC text mining. Sharing a sentence is not in itself a finding about the gene and the disease. The quoted sentences say what the papers report.
renal cell carcinoma (384 papers, 2005 to 2026). "von Hippel-Lindau (VHL) is a tumor suppressor frequently inactivated in renal cell carcinoma (RCC), and its loss is associated with aberrant DNA methylation." (PMID 41792232, 2026). "Von Hippel-Lindau (VHL) is a tumor suppressor frequently mutated in renal cell carcinoma (RCC) and its loss has been considered as a target for therapeutic exploitation." (PMID 40384876, 2025). "PT2385, a first-in-class orally available HIF-2α inhibitor, was originally developed to treat renal cell carcinoma (RCC) with Von Hippel-Lindau (VHL) mutations." (PMID 40095115, 2025). "Whole-genome sequencing identified a deletion mutation in exon 3 of the VHL gene, challenging the previous understanding that VHL deletion mutations are highly prevalent in hemangioblastoma and renal cell carcinoma but uncommon in pheochromocytoma." (PMID 41179499, 2025). "Approximately 80% of renal cell carcinomas (RCCs), similar to many other cancers, are associated with the loss of the von Hippel–Lindau (VHL) tumor suppressor gene, which is correlated with the Warburg effect and partially results from GLUT1 upregulation." (PMID 40941984, 2025). "We tested this in RCC4 cells, a renal cell carcinoma cell line carrying an inactivating VHL mutation that causes tonic HIF-1α stabilization even under normoxia." (PMID 40552983, 2025). "Inactivating mutations in the tumour suppressor gene VHL have been associated with several diseases, including pheochromocytoma, erythrocytosis, renal cell carcinoma, and cerebellar hemangioblastoma." (PMID 40320296, 2025). "von Hippel-Lindau (VHL) hereditary cancer syndrome is caused by mutations in the VHL tumor suppressor gene and is characterized by a predisposition to form various types of tumors, including renal cell carcinomas, hemangioblastomas, and pheochromocytomas." (PMID 39883230, 2025). "In VHL-deficient renal cell carcinoma (RCC), HIF-2α has been demonstrated to be the key oncogenic driver, while HIF-1α also contributes by supporting tumor metabolism." (PMID 40427061, 2025). "In renal cell carcinoma, some research has found that in patients with VHL gene mutations, the VHL gene can regulate tumor cell proliferation by controlling the Cl-/HCO3- exchange and Na+/H+ exchange activities in renal cancer cells." (PMID 40881716, 2025). "Age-related penetrance risks for retinal hemangioblastoma, central nervous system hemangioblastoma, renal cell carcinoma, pancreatic neuroendocrine tumors and pheochromocytoma/paraganglioma in carriers of the most frequent VHL mutations were assessed." (PMID 40202835, 2025). "HIF-2α expression has previously been demonstrated to be elevated in ccRCC caused by mutations in the von Hippel-Lindau (VHL) gene, which plays a vital role in the development of renal cell carcinoma." (PMID 39781455, 2025). "A low VHL mRNA expression level is generally associated with poor prognosis and shorter survival in several cancers, particularly renal cell carcinoma (RCC)." (PMID 40005423, 2025). "Genes implicated in renal cell carcinoma development—VHL, TSC1/2, and FLCN—will be used as examples to explore this concept, as well as how pathogenic mutations of tumor suppressors cause disease by disrupting protein chaperoning, maturation, and function." (PMID 39352796, 2024). "Function scores for 2,268 VHL single-nucleotide variants (SNVs) classify pathogenic alleles driving renal cell carcinoma and suggest new mechanisms by which variants impact function." (PMID 38969834, 2024). "Another significant discovery is that HIF-1 inhibits mitochondrial biogenesis and cellular respiration in VHL-deficient renal cell carcinoma by impeding C-MYC activity." (PMID 38928435, 2024). "The hypoxia-inducible factor 1α (Hif1α) is frequently upregulated in renal cell carcinoma, usually following a loss of function of the Von Hippel–Lindau tumor suppressor (VHL)." (PMID 39518998, 2024).
renal cell carcinoma (continued). "This SMURF2-mediated degradation mechanism bypasses the traditional VHL (von Hippel-Lindau) pathway, offering an alternative strategy to control HIF1α levels in cancers where VHL is mutated, such as in renal cell carcinoma." (PMID 39697237, 2024). "Somatic VHL mutations are frequently observed in renal cell carcinomas (RCCs), most commonly clear cell RCC (ccRCC)." (PMID 38969834, 2024). "Individuals affected by VHL disease, possessing a germline mutation of the VHL gene, manifest renal cell carcinomas and a series of tumors displaying hypervascular characteristics." (PMID 38666933, 2024). "VHL mutant heterozygotes are predisposed to multiple tumors, including cerebellar, spinal and retinal hemangioblastomas, renal cell carcinomas, pheochromocytomas and lymphatic sac tumors." (PMID 39336783, 2024). "Loss of the VHL tumor suppressor gene causes the most common and aggressive subtype of renal cell carcinoma, clear cell renal cell carcinoma (ccRCC)." (PMID 39352796, 2024). "When further stratified by tumor type, the prevalence of gene mutation in each tumor type was well below 1%, except for VHL with 44% in renal cell carcinomas (RCC)." (PMID 38864477, 2024). "Germline inactivation of the Von Hippel-Lindau (VHL) tumor suppressor is the defining hallmark in hereditary VHL disease and VHL-associated renal cell carcinoma (RCC)." (PMID 38339352, 2024). "Recent studies have presented the Von Hippel-Lindau (VHL), a tumor suppressor gene strongly associated with renal cell carcinoma, as a β-catenin target." (PMID 38087309, 2023). "Like Cluster 1 mutations in PPGL, hypoxia inducible factor (HIF) alterations due to VHL gene mutations are found in renal cell carcinoma, suggesting a potential similar molecular mechanism in PPGL." (PMID 36656469, 2023). "Partial VHL gene deletion suggests a higher risk of renal cell carcinoma than that seen in patients with complete deletions of the VHL gene." (PMID 37445575, 2023). "VHL gene mutations lead to the stability of HIF subunits and the constitutive activation of HIF‐mediated transcriptional pathways in patients with VHL, causing the progression of renal cell carcinoma." (PMID 36703877, 2023). "Chromosomal genetic disorders, such as von Hippel Lindau (VHL) syndrome with VHL gene mutation and hereditary leiomyomatosis and renal cell cancer with fumarate hydratase gene (FH) mutation, have been shown to be associated with the development of RCC." (PMID 37569676, 2023). "VHL gene mutation, deletion, and hypermethylation are closely related to the occurrence of renal cell carcinoma." (PMID 35035522, 2022). "The mutation rate of VHL in renal cell carcinoma was the highest, followed by PBRM1, TTN, and SETD2." (PMID 36186476, 2022). "Accordingly, VHL-related tumours, such as pheochromocytoma and renal cell carcinoma cells, display low mitochondrial content, suggesting that impaired mitochondrial biogenesis is linked to VHL tumorigenesis." (PMID 35760869, 2022). "Overexpression of Notch1 in mice with mutated VHL led to the development of renal cell carcinoma, structurally resembling the human pathology." (PMID 35055068, 2022). "A blind study that analyzed CTC in renal cell carcinomas carrying VHL mutation found the VHL mutation in all the CTCs isolated from the blood using ISET®." (PMID 35207452, 2022). "Renal cell carcinoma (RCC) are characterized by frequent VHL (Von Hippel-Lindau) mutations—which, by activating the pathways related to HIF-1α and further VEGF (Vascular Endothelial Growth Factor), makes them highly angiogenic tumors." (PMID 35625614, 2022). "Von Hippel Lindau(VHL)syndrome presents with cerebellar and spinal hemangioblastomas, renal cell cancer, neuroendocrine pancreatic tumor, and pheochromocytoma and it is caused by germline mutations in the VHL gene." (PMID 35875079, 2022).
renal cell carcinoma (continued). "We previously reported a case of VHL with a germline VHL mutation, 233 A > T, who underwent total pancreatectomy for multiple SCNs and right nephrectomy for renal cell carcinoma." (PMID 34191152, 2021). "It is a small molecule, which was first used as selective target VHL-deficient renal cell carcinoma cells." (PMID 34439338, 2021). "Animal studies revealed that three daily intraperitoneal doses of a soluble analogue of STF-31 effectively reduce the growth of tumors of VHL-deficient renal cell carcinoma cells in these mice." (PMID 34439338, 2021). "Mutations causing loss of function in VHL, an E3 ligase, result in tumoral development, especially renal cell carcinoma, as a result of the essential role of VHL in regulation of hypoxia-inducible factor 1 (HIF1) levels." (PMID 34577547, 2021). "Sporadic biallelic genetic or epigenetic VHL alterations, including VHL gene mutations, chromosome 3p deletions, or VHL gene methylations, are found in the vast majority of cell renal cell carcinomas and have widely been investigated over the past years." (PMID 32076485, 2020). "Consistently, CAFs has currently been reported to be indeed activated in renal cell carcinoma (RCC) with VHL gene malfunction in which RCC cells are deficient in assembling periFN matrices." (PMID 33158289, 2020). "Of note, renal cell carcinomas are associated with Von Hippel–Lindau (VHL) disease, an autosomal-dominant disorder caused by germline mutations of the VHL tumor-suppressor gene." (PMID 33167349, 2020). "First, the anti-CAIX monoclonal antibody G250 was successfully tested to image VHL-mutation-induced CAIX expression of renal cell carcinoma in 199316,17." (PMID 31827111, 2019). "Increased PD-L1 and HIF target genes (CAIX and GLUT1) expression have been observed in a renal cell carcinoma (RCC) model possessing a VHL mutation." (PMID 31835751, 2019). "Renal cell carcinomas with VHL deficiency and c-MYC amplification exhibit HIF-2α stabilization and PLA2R1 repression by promoter hypermethylation." (PMID 30939818, 2019). "Dagher J implied that wild-type von Hippel-Lindau (VHL) renal cell carcinomas were associated with lymph nodal metastases." (PMID 31215432, 2019). "In renal cell carcinoma, loss of the tumor suppressor von Hippel-Lindau (VHL) is widely regarded as an initiating event and associated with dramatic changes in global DNA methylation, potentially impacting subsequently acquired signaling mutations." (PMID 31784538, 2019). "VHL tumor suppressor gene mutations in humans are known to result in a predisposition to a range of tumors, such as renal cell carcinoma, hemangioblastoma of the central nervous system, and phaeochromocytoma." (PMID 30761299, 2019). "So, while HIF-1α antagonizes c-MYC-induced proliferation, HIF-2α increases it by potentiating the oncogenic effect of c-MYC in an in vitro model with VHL-deficient renal cell carcinoma." (PMID 30939818, 2019). "A well-known mechanism of ubiquitous CAIX upregulation is a mutation in the VHL, which is present in the majority of renal cell carcinomas (RCC)." (PMID 31827111, 2019). "Loss of VHL function frequently occurs in renal cell carcinoma (RCC) and its tumorigenicity is suppressed by gain of VHL function." (PMID 30902965, 2019). "In VHL, a mutation in the VHL-gene leads to a predisposition for cerebellar, spinal and retinal hemangioblastomas, renal cysts and renal cell carcinoma (RCC), pheochromocytomas and endolymphatic sac tumors." (PMID 29312473, 2018). "Deregulation of these two protein is involved in the development of VHL-associated clear-cell renal cell carcinoma with pVHL ectopic expression in VHL−/− renal cell carcinoma leading to suppression of tumor formation in mice." (PMID 29594129, 2018). "In renal cell carcinoma, loss of pVHL expression owing to genetic lesions of VHL gene (mutations or deletions) results in constitutive HIF-1 stabilization." (PMID 29662084, 2018).